MIF4GD (MIF4G domain containing)
Description:
Functions in replication-dependent translation of histone mRNAs which differ from other eukaryotic mRNAs in that they do not end with a poly-A tail but a stem-loop. May participate in circularizing those mRNAs specifically enhancing their translation.
Synonyms: SLIP1; AD023; MGC45027; MIFD
Tractability: PROTAC: ubiquitination databases record sites on it.
Gene: Protein-coding gene on chromosome 17 (75,266,228 to 75,271,237, reverse strand). Ensembl gene ENSG00000125457.
Subcellular location: Cytoplasm; Nucleus
Subcellular location (Human Protein Atlas): Nucleoli; Cytosol; Golgi apparatus
Gene Ontology:
Molecular function: identical protein binding; protein binding; translation activator activity; RNA binding
Biological process: cap-dependent translational initiation; regulation of translational initiation; positive regulation of translation
Cellular component: cytosol; histone mRNA stem-loop binding complex; nucleolus; cytoplasm; nucleus
Genetic constraint (gnomAD): Loss-of-function variants: 22 observed, 27.93 expected, observed/expected ratio (o/e) 0.79, 90% interval 0.56 to 1.12. The upper end of that interval is the gene's LOEUF score, 1.12, which puts it in group 4 of 6, group 1 being the genes least tolerant of losing a copy. Missense variants: 262 observed, 294.57 expected, observed/expected ratio (o/e) 0.89, 90% interval 0.8 to 0.99. Synonymous variants: 137 observed, 118.51 expected, observed/expected ratio (o/e) 1.16, 90% interval 1 to 1.33.
Homologues: Orthologues: chimpanzee MIF4GD (100% identical), dog MIF4GD (98% identical), pig MIF4GD (97% identical), rat Mif4gd (94% identical), guinea pig MIF4GD (94% identical), mouse Mif4gd (93% identical), zebrafish mif4gdb (74% identical), zebrafish mif4gda (64% identical), tropical clawed frog mif4gd (55% identical), Drosophila melanogaster CG13124 (23% identical), Caenorhabditis elegans F44A2.5 (18% identical). Paralogues in human: CTIF (31% identical), PAIP1 (21% identical).